GAS6 (growth arrest specific 6)
Diseases named in the same sentence as GAS6 in open-access papers (continued):
Sharing a sentence is not in itself a finding about the gene and the disease.
COVID-19 (17 papers, 2020 to 2024). A disease caused by infection with severe acute respiratory syndrome coronavirus 2. "Lastly, it is also worth noting that Gas6 and sAxl levels one year after hospital discharge remain associated with the class of severity reported in the acute phase of COVID-19, as this was already shown in baseline Gas6 and sAxl levels by other authors." (PMID 37047229, 2023). "Changes in these two parameters, cfDNA and GAS6 are indicative of an underlying interplay between the immune system and organ damage, contributing to mortality in COVID-19." (PMID 34344929, 2021). "Moreover, a prospective observational study showed that reduced levels of Gas6 and its soluble receptors, especially sAxl, were related to a history of post-COVID-19 hair loss." (PMID 38361939, 2024). "Due to the still limited number of scientific studies addressing this question, in this review we aimed to integrate the current knowledge of the Gas6/TAM axis with the pathophysiological mechanisms underlying COVID-19, with emphasis on the development of a fibrotic phenotype." (PMID 37630598, 2023). "Due to its immunomodulatory role, as well as its involvement in the modulation of inflammation and subsequent fibrotic evolution, the Gas6/TAM axis is emerging as an interesting research item in the context of the ongoing COVID-19 pandemic, caused by SARS-CoV-2." (PMID 36674471, 2023). "Interestingly, lower levels of Gas6 and sAxl were also associated with patients who had a history of hair loss following COVID-19." (PMID 37630598, 2023). "In conclusion, our findings confirm that hair loss is common among COVID-19 survivors and primarily suggest that this symptom may be associated with a derangement of the Gas6/TAM system." (PMID 37047229, 2023). "Thus, the aim of the present study was to investigate a possible association between circulating Gas6, sAxl, and sMer levels with long-term sequelae in COVID-19 survivors." (PMID 37047229, 2023). "Decreased levels of Gas6 and sAxl were associated with a history of hair loss following COVID-19." (PMID 37047229, 2023). "In critically ill COVID-19 patients, alveolar damage is associated with vessel injury and thrombotic activation and an increase in Gas6/TAM levels in these patients might explain the abnormal coagulation parameters linked to COVID-19." (PMID 37630598, 2023). "Since the alveolar damage in COVID-19 is associated to vessel injury with diffuse thrombotic activation, the observed dysregulation in Gas6/TAM pathway can be associated also to these events as a link between inflamed and damaged endothelium and platelet activation." (PMID 35531477, 2022). "Although cfDNA, H3, NE, sAXL and GAS6 were all elevated in COVID-19 positive patients at admission, and some of these associated with development of organ dysfunction, linear regression analysis showed that none of these day-1 parameters was a good predictor of final outcome." (PMID 34344929, 2021). "It is of potential interest that increased levels of another vitamin K-dependent protein and biomarker of vitamin K status, plasma growth arrest-specific factor 6 (GAS6), have been found to be associated with disease severity and mortality in hospitalized COVID-19 patients." (PMID 34207745, 2021). "Indeed, in COVID-19 patients, Gas6 levels increase progressively with the severity of the disease and predict adverse outcomes; a derangement of this system has also been associated with hair loss one year after hospital discharge due to COVID-19." (PMID 39057085, 2024). "Considering its effect in modulating host immune responses, the Gas6/TAM axis has also gained attention in the context of COVID-19 studies, showing a direct correlation between plasma Gas6 levels and disease severity." (PMID 36674471, 2023). "More recently, we first showed that the levels of sAxl and Gas6 in post-COVID-19 subjects, one year after hospital discharge, were still associated with the class of severity reported during the acute phase of the disease." (PMID 37630598, 2023).
COVID-19 (continued). "Since the publication of that work, many research groups focused their attention on this signaling pathway activation in COVID-19 to disclose the existing correlations between the Gas6/TAM axis and disease evolution." (PMID 36674471, 2023). "Since the beginning of the pandemic, many research groups have highlighted a direct correlation between Gas6 plasma levels and COVID-19 severity." (PMID 37108262, 2023). "Due to the rapidly evolving COVID-19 pandemic, Gas6/TAM axis activation has gained interest due to its involvement in inflammatory responses and subsequent fibrosis, two features strictly related to severe SARS-CoV-2 clinical manifestations." (PMID 36674471, 2023). "Recently, our group confirmed the correlation between Gas6 levels at the time of hospital admission and an adverse outcome in hospitalized COVID-19 patients." (PMID 36674471, 2023). "Even if the majority of the research papers are focused on the Gas6/TAM axis involvement in COVID-19, interesting results also come from in vitro research." (PMID 36674471, 2023). "Due to the limited number of studies published on the Gas6/TAM system involvement in COVID-19 pathogenesis, further studies are warranted to better elucidate the role of this pathway in this disease." (PMID 36674471, 2023). "Due to the rapidly evolving COVID-19 pandemic, this review will focus on Gas6/TAM axis activation in SARS-CoV-2 infection, where de-regulated inflammatory responses and fibrosis represent a relevant feature of severe disease manifestation." (PMID 36674471, 2023). "Some authors have recently highlighted the role of the Gas6/TAM system as potentially relevant also in COVID-19 pathogenesis." (PMID 37630598, 2023). "It is important to note that almost all reports in the literature about the involvement of the Gas6/TAM axis in COVID-19 focus on the adult population." (PMID 36674471, 2023). "In COVID-19, plasma Gas6 and sTAM levels have been shown to reflect disease severity and have been identified as possible early biomarkers of disease prognosis." (PMID 37630598, 2023). "A total of 263 subjects underwent a structured clinical evaluation one year after their hospital discharge for COVID-19, and they consented to donate a blood sample to measure their circulating Gas6, sAxl, and sMer levels." (PMID 37047229, 2023). "Altogether, our results highlighted the involvement of Gas6/TAM system in COVID-19 evolution, in particular when hyperinflammation and immune response dysregulation is present." (PMID 35531477, 2022). "Consistent with lower levels of GAS6 in patients with mild/moderate disease, GAS6 levels in COVID-19 patients correlated negatively with PaO2/FiO2 ratio." (PMID 34143756, 2021). "AXL is a candidate receptor for SARS-CoV-2, particularly in the respiratory system, and the GAS6/AXL axis is targeted in current clinical trials against COVID-19." (PMID 33810394, 2021). "GAS6, lower than normal control levels in mild/moderate COVID-19 on hospital admission, remained low after COVID-19." (PMID 34143756, 2021). "GAS6 plasma level is increased in COVID-19 patients compared with controls and decreased over time in patients surviving to 30 days post ICU admission." (PMID 34944005, 2021). "COVID-19 patients with PaO2/FiO2 > 200 had lower plasma GAS6 levels than those with PaO2/FiO2 ≤ 200, and optimum cut-off plasma levels of GAS6 < 24 ng/mL detected those more likely to maintain good lung function (PaO2/FiO2 > 200)." (PMID 34143756, 2021). "In our COVID-19 cohort, GAS6 concentrations at ICU admission more than doubled those of non-COVID-19 IC patients." (PMID 34344929, 2021). "In summary, these results support a relevant role of the GAS6/AXL system in the immune response against COVID-19, suggesting them as early markers of disease prognosis and GAS6/AXL targeting as plausible clinical therapy for COVID-19 patients." (PMID 33810394, 2021).
COVID-19 (continued). "Indeed, in previous papers, higher plasma Gas6 concentrations upon hospital admission during the acute phase of COVID-19 predicted a more severe evolution." (PMID 37047229, 2023). "So that, plasma Gas6 measurement at the baseline might represent a promising biomarker in COVID-19 to help to stratify patients' severity." (PMID 35531477, 2022). "Concerning Gas6 levels, our results are not only a simple confirmation of these previous data but add a more precise context where plasma Gas6 measurement is worthwhile: the patients with COVID-19 needing hospitalization due to moderate to severe respiratory failure needing noninvasive ventilation." (PMID 35531477, 2022). "First, cfDNA, NE, histones and GAS6/AXL are activated in severe COVID-19." (PMID 34344929, 2021). "However, GAS6 levels were lower in patients with milder acute COVID-19 and in post–COVID-19 subjects in whom acute inflammation had resolved, compared with healthy donors and patients with severe COVID-19." (PMID 34143756, 2021). "The specific increase of GAS6 over sAXL in COVID-19 could reflect a need of free, active GAS6 in this condition." (PMID 34344929, 2021). "cfDNA, extracellular histones and GAS6 are implicated in regulation of inflammatory and hemostatic pathways in the context of severe viral infections and ARDS, all of which are implicated in COVID-19." (PMID 34344929, 2021). "According to this view, GAS6 and TAMs would be expected to participate in COVID-19 viral entry." (PMID 32998369, 2020). "Taken together, these results support the hypothesis that a dysregulation in the Gas6/TAM axis could play a relevant role in modulating the course of COVID-19 and suggest that plasma Gas6 may represent a promising prognostic laboratory parameter for this condition." (PMID 35531477, 2022). "Additionally, we confirmed that Gas6/TAM system is involved in COVID-19 with severe evolution and may be a promising target for further research on COVID-19 pathophysiology." (PMID 35531477, 2022). "GAS6 was higher in COVID-19 and non–SARS-CoV-2 pneumonia patients > 70 years old and higher in COVID-19 patients with arterial hypertension, diabetes mellitus, and ischemic cardiopathy; thus, age and comorbidities may confound interpretation of increased GAS6 in COVID-19." (PMID 34143756, 2021). "Prognostically, low levels of GAS6 at the time of hospital admission and/or before antiinflammatory treatment were predictive of low risk for ICU transfer; for example, 6.5% of COVID-19 patients with GAS6 < 24 ng/mL required transfer to ICU compared with 44.4% of those with GAS6 ≥ 24 ng/mL." (PMID 34143756, 2021). "Information about Gas6/TAM’s physiologic role is still evolving and, in the last few years, such signaling pathways have been identified as a prognostic biomarker for COVID-19 evolution." (PMID 36674471, 2023). "This review makes a strong case for further research focusing on the Gas6/TAM axis as a pharmacological target to manage different disease conditions, such as chronic fibrosis or COVID-19." (PMID 36674471, 2023). "At multivariate analysis, after correction for demographic and COVID-19 severity variables (NEWS2 and PiO2/FiO2), only Gas6 measured at baseline predicted an adverse prognosis with an odds ratio of 1.03 (C.I. 1.01-10.5)." (PMID 35531477, 2022). "In COVID-19 and non-COVID-19 ICU patients, the GAS6 concentration at study inclusion was 24.2 (16.8–31.9) ng/mL and 12.1 (9.5–15.9) ng/mL respectively, indicating a significant difference between both groups (p < 0.001)." (PMID 34344929, 2021). "We investigated the persistence of increased plasma SPP1, S100A12, GAS6, and PROS1 into the SARS-CoV-2– post–COVID-19 phase, often characterized by complex pathologies." (PMID 34143756, 2021). "Second, cfDNA, NE, histones and GAS6/AXL are related to the severity of illness and reflect organ dysfunction in severe COVID-19." (PMID 34344929, 2021).
COVID-19 (continued). "Highlighting the importance of the treatment schedule, recent data revealed that GAS6 and AXL significantly increased in plasma of COVID-19 patients as compared to controls, while GAS6 decreased over time in patients surviving to 30 days post ICU admission." (PMID 32998369, 2020). "This fact, together with the crucial function of TAM-related signaling in the regulation of inflammation and the observed predictive role of circulating Gas6 and TAM with disease severity, has confirmed the importance of further investigating this system in the COVID-19 context." (PMID 37630598, 2023). "Despite the existing evidence of the reliability of Gas6 as a COVID-19 negative disease evolution marker, to date, investigations about its predictive role for long-term lung fibrosis development in survivors are still lacking." (PMID 36674471, 2023). "The finding that Gas6 plasmatic levels correlate with COVID-19 severity is not surprising from the pathophysiologic point of view." (PMID 35531477, 2022). "Furthermore, Huckriede and colleagues studied Gas6 in severe, ICU admitted, COVID-19 patients, observing lower levels of this cytokine in survivors compared to nonsurvivors." (PMID 35531477, 2022). "Next, we investigated whether concomitant pharmacological drug treatment, demographic factors (age and sex), and COVID-19 comorbidities contributed to the plasma levels of SPP1, S100A12, GAS6, and PROS1." (PMID 34143756, 2021). "cfDNA, H3, NE, GAS6 and AXL were increased in COVID-19 patients compared to controls." (PMID 34344929, 2021). "Stratification of patients by symptoms showed that SPP1 and S100A12 levels remained increased and GAS6 decreased in convalescent COVID-19 patients, irrespective of symptom category." (PMID 34143756, 2021). "Furthermore, exploring the Gas6/TAM system as a player in disease development and progression could provide new therapeutic strategies for COVID-19 patients or patients experiencing other fibrotic conditions." (PMID 37630598, 2023). "Because of the possible contribution of GAS6 to neutrophil and platelet recruitment and aggregation, these observations may suggest GAS6/AXL as a promising target for the prevention and treatment of pulmonary failure and thrombotic complications of COVID-19." (PMID 32998369, 2020). "However, GAS6 and TAMs have not been evaluated in COVID-19 patients at emergency admission." (PMID 33810394, 2021). "Despite these facts, to date, no data have been reported on plasma concentrations of GAS6 and TAM receptors at the time of hospital admission of patients with COVID-19." (PMID 33810394, 2021).
gastric cancer (16 papers, 2011 to 2026). A primary or metastatic malignant neoplasm involving the stomach. "Previous studies have underscored the critical role of the GAS6/AXL signaling axis in driving the aggressive behavior of gastric carcinoma cells, particularly through interactions with cancer-associated fibroblasts (CAFs)." (PMID 39597836, 2024). "On the other hand, GAS6 has been demonstrated to participate in a signaling pathway which promotes cellular survival and invasion of gastric cancer cells through the Akt pathway." (PMID 31749921, 2019). "In gastric cancer, there is one report that administration of recombinant Gas6 phosphorylated Axl in GC cell lines, and then enhanced cellular survival and suppressed apoptosis via Akt pathway." (PMID 29228560, 2017). "In addition, studies have shown that CAF-derived growth arrest-specific 6(GAS6) in gastric cancer can promote the proliferation and migration of gastric cancer cells by phosphorylating receptor tyrosine kinase (AXL)." (PMID 40485724, 2025). "Furthermore, Axl plays a critical role in reshaping the tumor microenvironment in gastric cancer, promoting immune evasion, therapy resistance, and tumor progression through the GAS6–Axl axis." (PMID 41011010, 2025). "The results showed that CAFs are closely adjacent to cancer cells in gastric cancer tissues, and the interaction between CAFs and cancer cells promotes the progression of gastric cancer through the secretion of various cytokines and growth factors, such as GAS6 and AXL." (PMID 40485724, 2025). "Moreover, GAS6 is overexpressed in glioblastoma and gastric cancers." (PMID 31700829, 2019). "The in vitro experiments using recombinant Gas6 and a decoy-receptor of AXL showed that activation of Gas6-AXL signaling axis leads to the inhibition of apoptosis and exacerbation of AKT-dependent survival and invasion of gastric cancer cells." (PMID 37469409, 2023). "Gas6-AXL signaling pathway has been shown to enhance cell survival and suppress apoptosis in gastric cancer cells through activation of the AKT pathway." (PMID 37469409, 2023). "For instance, high levels of Gas6 and AXL mRNA and proteins were revealed in human gastric cancer cell lines and tissue samples, and Gas6 expression was significantly correlated with metastases to lymph nodes." (PMID 37469409, 2023). "High mRNA and protein expression of Gas6 and AXL has been reported in human gastric cancer cell lines and tissues." (PMID 37469409, 2023).